MVD (mevalonate diphosphate decarboxylase)
Description:
Catalyzes the ATP dependent decarboxylation of (R)-5-diphosphomevalonate to form isopentenyl diphosphate (IPP). Functions in the mevalonate (MVA) pathway leading to isopentenyl diphosphate (IPP), a key precursor for the biosynthesis of isoprenoids and sterol synthesis.
Synonyms: MDDase; MPD; FP17780; POROK7
Tractability: Small molecule: it has a high-quality binding pocket; it belongs to a druggable protein family. PROTAC: ubiquitination databases record sites on it; its protein half-life has been measured; a small molecule that binds it is known.
Target class: Enzyme; Lyase
Gene: Protein-coding gene on chromosome 16 (88,651,934 to 88,663,161, reverse strand). Ensembl gene ENSG00000167508.
Subcellular location: Cytoplasm
Subcellular location (Human Protein Atlas): Cytosol; Cell Junctions
Pathways (Reactome):
Metabolism: Activation of gene expression by SREBF (SREBP); Lanosterol biosynthesis
Metabolism of proteins: Synthesis of dolichyl-phosphate
Gene Ontology:
Molecular function: diphosphomevalonate decarboxylase activity; Hsp70 protein binding; protein homodimerization activity; carboxy-lyase activity
Biological process: isoprenoid biosynthetic process; positive regulation of cell population proliferation; cholesterol biosynthetic process; farnesyl diphosphate biosynthetic process, mevalonate pathway; geranylgeranyl diphosphate biosynthetic process; isopentenyl diphosphate biosynthetic process, mevalonate pathway; zymosterol biosynthetic process
Cellular component: cytoplasm; cytosol; peroxisome
Genetic constraint (gnomAD): Loss-of-function variants: 53 observed, 38.97 expected, observed/expected ratio (o/e) 1.36, 90% interval 1.09 to 1.71. The synonymous counts are far from expectation, so gnomAD's model fits this gene poorly and the ratio says little. Missense variants: 663 observed, 523.17 expected, observed/expected ratio (o/e) 1.27, 90% interval 1.19 to 1.35. Synonymous variants: 287 observed, 220.51 expected, observed/expected ratio (o/e) 1.3, 90% interval 1.18 to 1.43.
Homologues: Orthologues: chimpanzee MVD (99% identical), macaque MVD (96% identical), dog MVD (86% identical), rat Mvd (84% identical), mouse Mvd (84% identical), pig MVD (81% identical), guinea pig MVD (81% identical), tropical clawed frog mvd (66% identical), zebrafish mvda (64% identical), Drosophila melanogaster Mvd (46% identical), Caenorhabditis elegans Y48B6A.13 (33% identical).
Diseases named in the same sentence as MVD in open-access papers:
MVD is named in the same sentence as 18 diseases in open-access papers, as found by Europe PMC text mining. Sharing a sentence is not in itself a finding about the gene and the disease. The quoted sentences say what the papers report.
porokeratosis (2 papers, 2015 to 2024). A clonal proliferation of abnormal keratinocytes characterized by the development of localized or multiple atrophic skin patches surrounded by an annular keratotic ring called cornoid lamella. "Mutations of the MVD gene have been reported to be involved in porokeratosis, a disorder of defective keratinization." (PMID 38898137, 2024). "Mutations in some of the newly identified genes were instead linked to porokeratosis affecting specific areas of the body; for example, PMVK and MVD mutations are linked to porokeratosis localized to the genitals and around the eyes, respectively." (PMID 26202976, 2015). "This search identified mutations in three additional genes (called PMVK, MVD and FDPS) that are all linked to porokeratosis." (PMID 26202976, 2015).
viral infection (2 papers, 2018 to 2025). "Genes controlling the key steps in cholesterol biosynthesis, such as FDPS, ACAT2, MVD, LSS, and FDFT1, were transcriptionally commonly suppressed upon viral infection at 48 hpi." (PMID 40857262, 2025). "The mRNA expression of these five genes, HMGCS1, HMGCR, MVD, MVK, and FDPS, was consistently decreased after M1 virus infection in both HCT-116 and SW1990 cell lines." (PMID 29670091, 2018).
optic neuritis (1 paper, 2023). Optic neuritis is inflammation of the optic nerve, the nerve that carries the visual signal from the eye to the brain.The conditionmay cause sudden, reduced vision in the affected eye(s). "Peripapillary choroidal MvD was detected in 20 out of 48 eyes with optic neuritis (41.7%; designated as MvD+ group)." (PMID 37104301, 2023).
ovarian dysfunction (1 paper, 2023). The inability of the ovaries to function. "Among the genes we identified through coexpression of three datasets, PNPLA3, MVD, MMP9, oncostatin M (OSM), LCK, triggering receptor expressed on myeloid cells 1 (TREM1), FADS2, proprotein convertase subtilisin/kexin type 9 (PCSK9), and C3 are involved in lipid metabolism and ovarian dysfunction." (PMID 37537636, 2023).
uveitis (1 paper, 2020). An inflammatory process affecting a part of or the entire uvea. "The second cluster (C2) of genes was relatively higher expressed in JIA cases without uveitis and contained genes involved in cholesterol biosynthesis and mevalonate pathway (e.g., MVD, FDPS, SEC23A)." (PMID 33042130, 2020).
cancer (3 papers, 2021 to 2025). A tumor composed of atypical neoplastic, often pleomorphic cells that invade other tissues. "The cellular lysates from H1299 and MDA-MB-231 cancer cells subjected to 24 h serum deprivation exhibited about a two-fold increase in abundance of HMGCS1 and MVD proteins compared with cells cultured with serum." (PMID 41303417, 2025).
MVD also shares sentences with these, for which no sentence is quoted: tumor (2 papers); COVID-19 (1); dyslipidemia (1); Hypercholesterolemia (1); Hypertension (1); infection (1); infectious disease (1); Listeria infection (1); nonsyndromic hearing impairment (1); optic nerve disorder (1); ovarian carcinoma (1); pituitary tumour (1).